EGR2 (early growth response 2)
Description:
Sequence-specific DNA-binding transcription factor. Plays a role in hindbrain segmentation by regulating the expression of a subset of homeobox containing genes and in Schwann cell myelination by regulating the expression of genes involved in the formation and maintenance of myelin (By similarity). Binds to two EGR2-consensus sites EGR2A (5'-CTGTAGGAG-3') and EGR2B (5'-ATGTAGGTG-3') in the HOXB3 enhancer and promotes HOXB3 transcriptional activation (By similarity). Binds to specific DNA sites located in the promoter region of HOXA4, HOXB2 and ERBB2 (By similarity). Regulates hindbrain segmentation by controlling the expression of Hox genes, such as HOXA4, HOXB3 and HOXB2, and thereby specifying odd and even rhombomeres (By similarity). Promotes the expression of HOXB3 in the rhombomere r5 in the hindbrain (By similarity). Regulates myelination in the peripheral nervous system after birth, possibly by regulating the expression of myelin proteins, such as MPZ, and by promoting the differentiation of Schwann cells (By similarity). Involved in the development of the jaw openener musculature, probably by playing a role in its innervation through trigeminal motor neurons (By similarity). May play a role in adipogenesis, possibly by regulating the expression of CEBPB (By similarity). E3 SUMO-protein ligase helping SUMO1 conjugation to its coregulators NAB1 and NAB2, whose sumoylation down-regulates EGR2 transcriptional activity.
Synonyms: KROX20; AT591; CMT1D; CMT4E
Tractability: PROTAC: UniProt records ubiquitination sites on it.
Gene: Protein-coding gene on chromosome 10 (62,811,996 to 62,819,167, reverse strand). Ensembl gene ENSG00000122877.
Subcellular location: Nucleus
Subcellular location (Human Protein Atlas): Nucleoplasm
Pathways (Reactome):
Developmental Biology: Activation of anterior HOX genes in hindbrain development during early embryogenesis; EGR2 and SOX10-mediated initiation of Schwann cell myelination; Transcriptional regulation of white adipocyte differentiation
Signal Transduction: NGF-stimulated transcription
Gene Ontology:
Molecular function: DNA-binding transcription activator activity, RNA polymerase II-specific; DNA-binding transcription factor activity; DNA-binding transcription factor activity, RNA polymerase II-specific; protein binding; RNA polymerase II cis-regulatory region sequence-specific DNA binding; sequence-specific DNA binding; sequence-specific double-stranded DNA binding; ubiquitin protein ligase binding; chromatin binding; RNA polymerase II-specific DNA-binding transcription factor binding; SUMO ligase activity; transcription cis-regulatory region binding; DNA binding
Biological process: positive regulation of transcription by RNA polymerase II; brain development; facial nerve structural organization; fat cell differentiation; peripheral nervous system development; positive regulation of DNA-templated transcription; positive regulation of myelination; positive regulation of Schwann cell differentiation; protein export from nucleus; protein sumoylation; regulation of transcription by RNA polymerase II; rhombomere 3 structural organization; rhombomere 5 structural organization; Schwann cell differentiation; skeletal muscle cell differentiation; aorta development
Cellular component: chromatin; cytoplasm; nucleoplasm; nucleus
Genetic constraint (gnomAD): Loss-of-function variants: 4 observed, 22.8 expected, observed/expected ratio (o/e) 0.18, 90% interval 0.085 to 0.4. The upper end of that interval is the gene's LOEUF score, 0.4, which puts it in group 1 of 6, group 1 being the genes least tolerant of losing a copy. Missense variants: 458 observed, 654.08 expected, observed/expected ratio (o/e) 0.7, 90% interval 0.65 to 0.76. Synonymous variants: 282 observed, 267.68 expected, observed/expected ratio (o/e) 1.05, 90% interval 0.95 to 1.16.
Gene-disease validity (ClinGen):
ClinGen rates the evidence that EGR2 causes each of these diseases.
Charcot-Marie-Tooth disease (semidominant): Definitive. An inherited degenerative disorder involving the peripheral nerves.
Homologues: Orthologues: chimpanzee EGR2 (100% identical), macaque EGR2 (96% identical), guinea pig EGR2 (95% identical), pig EGR2 (93% identical), dog EGR2 (93% identical), rabbit EGR2 (93% identical), mouse Egr2 (89% identical), rat Egr2 (86% identical), tropical clawed frog egr2 (63% identical), zebrafish egr2b (62% identical). Paralogues in human: EGR3 (43% identical), EGR1 (40% identical), EGR4 (26% identical), WT1 (23% identical).
Diseases named in the same sentence as EGR2 in open-access papers:
EGR2 is named in the same sentence as 169 diseases in open-access papers, as found by Europe PMC text mining. Sharing a sentence is not in itself a finding about the gene and the disease. The quoted sentences say what the papers report.
gastric cancer (21 papers, 2011 to 2025). A primary or metastatic malignant neoplasm involving the stomach. "MiR-20a was also proved to enhance gastric cancer resistance to ADR via inhibiting expression of early growth response 2 (EGR2), a member of a multi-gene family which encoding C2H2-type zinc-finger proteins." (PMID 32192494, 2020). "For instance, LINC01939 directly binds to miR-17-5p and functions as a sponge of miR-17-5p to up-regulate the expression of EGR2 (the target of miR-17-5p) protein in gastric cancer." (PMID 35833119, 2022). "Together, these results demonstrated that knockdown of EGR2 promotes gastric cancer cells’ growth and inhibits their apoptosis." (PMID 34764975, 2021). "Altogether, these findings revealed miR-25 as a regulator of gastric cancer cell growth and apoptosis through targeting EGR2." (PMID 34764975, 2021). "To investigate the function of EGR2 in gastric cancer cells’ growth and apoptosis, we used EGR2 siRNA to reduce the expression of EGR2." (PMID 34764975, 2021). "Mechanically, we demonstrated that EGR2 was a target gene of miR-25 by dual-luciferase reporter gene assay in gastric cancer cells." (PMID 34764975, 2021). "As a vital TF exhibiting higher transcriptional activity in PTC samples than in control, EGR2 functions as a tumor suppressor that is generally decreased in numerous cancer types such as ovarian and gastric cancer." (PMID 29351231, 2018). "In gastric cancer cells, miR-150 promotes cell survival by repressing the transcription of EGR2, a pro-apoptotic gene." (PMID 26715362, 2015). "Knockdown of EGR2 promotes gastric cancer cell growth and suppresses apoptosis." (PMID 38911380, 2024). "Previous reports have indicated that EGR2 could inhibit the metastasis of gastric cancer, regulate the growth and apoptosis of gastric cancer, and inhibit the tumor growth of thyroid carcinoma and papillary thyroid carcinoma." (PMID 37529797, 2022). "miR-25 inhibitor and EGR2 siRNA were co-transfected into gastric cancer cells." (PMID 34764975, 2021). "It is reported that EGR2 inhibited gastric cancer cell proliferation and cell invasion, which suggested that it might act as a antioncogene." (PMID 34130587, 2021). "Moreover, knockdown of EGR2 promoted gastric cancer cell growth and inhibited their apoptosis by flow cytometry detection." (PMID 34764975, 2021). "Additionally, findings deriving from gastric cancer research revealed that miR-150-5p inhibits apoptosis in gastric cancer cells by targeting the pro-apoptotic gene EGR2." (PMID 33806113, 2021). "Besides the sensitivity accommodation, upregulation of Egr2 also exerted inhibition effect on invasion and migration of gastric cancer, which was also observed in HepG2 cells in our research." (PMID 33023539, 2020). "Knockdown of EGR2 could promote gastric cancer cells’ growth and inhibit their apoptosis." (PMID 34764975, 2021). "The result showed that knockdown of EGR2 could inhibit gastric cancer cells’ apoptosis." (PMID 34764975, 2021). "In this study, we systematically delineated the transcriptional regulatory landscape of THY1 in gastric cancer by identifying six robust putative regulators—PRRX1, TWIST1, SNAI2, MEIS3, VENTX, and EGR2—through an integrative multicohort approach." (PMID 40476057, 2025). "For example, miR-20a could confer DDP resistance by silencing EGR2 and cylindromatosis (CYLD) in gastric cancer cells." (PMID 32192494, 2020).
breast carcinoma (13 papers, 2007 to 2023). "By joint analysis of gene expression data from previous studies, we constructed interrelationships of mainly CRHBP, ICAM1, PLAGL1, DNMT1, CNTLN, DKK1, and EGR2 with preterm birth, infant disease, and breast cancer." (PMID 36788602, 2023). "EGR1 and EGR2 directly regulate a series of classical tumor suppressors, and experimental interference of their expression dramatically alter breast cancer cell growth rates." (PMID 21627793, 2011). "This analysis indicates that the predicted PTB-related genes including ICAM1, CRHBP, PLAGL1, EGR2, CNTLN, and DKK1 play an important role in preforming biological activities associated with PTB, infant disease, and possibly breast cancer, due to the gestational age-induced." (PMID 36788602, 2023). "EGR2 is expressed in breast cancer cell lines, particularly the more aggressive triple negative subtypes and may be regulated in part by Epidermal Growth Factor (EGF) family members." (PMID 28687085, 2017). "Similarly, the top hub TFs we found in the integrated network such as SP1, SP2, TCF12, MYC, JUN and EGR2, were also well-known regulators in breast cancer." (PMID 26763900, 2015). "In all subtypes of breast cancer, the mRNA levels of EGR1, EGR2, and EGR3 were all lower in malignant breast tissues compared with normal tissues." (PMID 33614706, 2020). "As indicated by the results, the transcriptional levels of EGR1, EGR2, and EGR3 were significantly reduced in patients with BRCA (p < 0.05), whereas the expression level of EGR4 was very low in both breast cancer and normal breast tissues." (PMID 33614706, 2020). "Another example relevant for breast cancer is the hsa-miR-17-5p/EREG pair of miRNA and predicted target gene that putatively form FFLs with E2F1, EGR2, FOXJ2 and RUNX1." (PMID 17971223, 2007). "Hence, we attempted to explore the potential mechanism capable of explaining why higher expression levels of EGR1, EGR2, and EGR3 predicted better outcomes in patients with breast cancer." (PMID 33614706, 2020). "Conversely, breast cancer cells overexpressing SFRP1 (MCF7-SFRP1) express less EGR2 when compared with vector transfected cells (MCF7-pCDNA) and exogenous rSFRP1 treatment reduces EGR2 expression in MCF7 cells." (PMID 28687085, 2017). "However, how EGR2 contributes to breast cancer however is not clear, its expression has been suggested to drive both the expression of both Erbb2, as well as aromatase expression." (PMID 28687085, 2017). "When we further tested the effect of SFRP1 expression in a panel of breast cancer cell lines, we found that SFRP1 reduced the mRNA levels of EGR2 in T47D cells but not in TMX2–28 cells (a Tamoxifen resistant variant of MCF7) or MDA-MB-231 cells." (PMID 28687085, 2017). "A few genes previously reported to be induced by acidosis in breast cancer cells, including TXNIP, ARRDC4 and EGR2, were also noted to be induced in both HUVEC/Vector and HUVEC/GPR4 cells." (PMID 23613998, 2013).
viral infection (13 papers, 2015 to 2025). "Deficiency of Egr2 and 3 leads to altered expression of these transcription factors and severe inflammatory pathology during viral infection." (PMID 29314730, 2018). "Consistent with CD2-Egr2/3−/− mice, Egr2- and Egr3-deficient T cells in the chimeras displayed impaired expansion and enhanced differentiation in response to viral infection." (PMID 28487311, 2017). "The binding of T-bet to the CNS-34, CNS-22, and CNS+30 enhancer regions of the Ifng locus was increased in Egr2/3-deficient CD4 T cells compared with WT counterparts in response to virus infection." (PMID 28455436, 2017). "FR4+Egr2+ cells express genesets implicated in memory Tfh cell maintenance in the steady state and support the development of germinal centers and anti‐viral antibody production in response to viral infection." (PMID 39568245, 2025). "T-bet is highly expressed in Egr2- and Egr3-deficient T cells in response to viral infection, which is in direct contrast to a recent report that Egr2 is required for T-bet expression and that Egr2 deficiency leads to defects in both T cell activation and effector differentiation." (PMID 28487311, 2017). "The Egr2 and 3 transcription factors are important for the development of viral responding Tfh cells following viral infection by direct regulation of Bcl6 expression." (PMID 39568245, 2025). "Egr2/3 are essential for supporting proliferation of naïve T cells in responses to antigen stimulation and the development of Tfh cells during viral infection." (PMID 39568245, 2025). "The induction of EGR1 following viral infection stimulates multiple inflammatory factors (EGR2 and EGR4) and mediates host cell response to viruses." (PMID 37998351, 2023). "The similar transcriptional profiles and impairments in proliferation seen in both Egr2/3−/− PD-1high MP CD4 T cells and Egr2/3−/− effector T cells responding to viral infection indicates a general function of Egr2/3 is to support T-cell proliferation." (PMID 32709717, 2020). "To further assess the temporal expression of Egr2 during viral infection, we isolated CD45.2+GFP-Egr2highCD44highCD8+ and CD45.2+GFP-Egr2lowCD44highCD8+ cells and adoptively transferred them to separate CD45.1+ naive mice." (PMID 28487311, 2017). "Egr2 and 3 are transiently expressed in naive T cells in response to acute viral infection, whereas the expression is sustained in chronic infection and tolerogenic conditions." (PMID 28487311, 2017). "Recently, Egr2 was found to be important for differentiation of T cells in response to viral infection by directly binding to the Tbx21 locus and promoting the expression of T-bet." (PMID 28487311, 2017). "Enforced expression of BCL6 in EGR2/3-deficient CD4 T cells partially restored Tfh differentiation and GC formation in response to virus infection." (PMID 25979336, 2015). "We found that the differentiation of Tfh cells in CD2-Egr2−/−Egr3−/−mice, which lack EGR2 and -3 in B and T cells, was severely defective, resulting in failure to form GCs after virus infection." (PMID 25979336, 2015). "Egr2/3‐regulated genes involved in the development of Tfh cells in response to viral infection." (PMID 39568245, 2025). "Therefore, in contrast to transient expression in effector T cells in response to viral infection, Egr2 expression is maintained in PD-1high MP CD4 T cells." (PMID 32709717, 2020). "However, in response to viral infection, Egr2 and 3 in T cells have been found to promote antigen induced proliferation." (PMID 29314730, 2018). "Next we assessed regulation of Egr2 expression in vivo in response to viral infection." (PMID 28487311, 2017). "In this study, we assessed the mechanisms of Egr2 and 3 function in the regulation of effector cell differentiation in response to viral infection and induction of Th differentiation, with a specific focus on the effect on T-bet function in the regulation of IFN-γ production." (PMID 28455436, 2017).
viral infection (continued). "Thus, temporally regulated expression of Egr2 and 3 induced in naive T cells in response to virus infection is essential for optimal adaptive immune responses with minimum pathology." (PMID 28487311, 2017). "Therefore, we assessed the differentiation of effector CD4 and CD8 T cells in response to viral infection by analysis of production of effector cytokines and granzyme B. We discovered that Egr2 and 3 promoted clonal expansion but profoundly suppressed differentiation of effector CD4 and 8 T cells." (PMID 28487311, 2017). "We identified 31 differentially expressed circRNAs and 7 mRNAs (HSPA8, HSPA1B, EGR2, CXCR4, SOCS3, NOTCH3, and ZNF527) related to viral infection." (PMID 41471859, 2025). "T-bet expression was not defective in CD4 and CD8 T cells from CD2-specific Egr2/3−/− mice in response to virus infection; indeed, T-bet+ CD4 T cells were higher in CD2-specific Egr2/3−/− mice." (PMID 28455436, 2017). "Transcriptional profiling demonstrated that Egr2 and 3 are upstream regulators of genes required for expansion and suppression of effector differentiation in both CD4 and CD8 T cells in response to viral infection." (PMID 28487311, 2017). "Among the proliferation regulators, Egr2 and 3 directly control the expression of Myc in both CD4 and CD8 T cells in response to viral infection, which is a key transcription factor for T cell proliferation." (PMID 28487311, 2017). "Collectively, our data highlight the overlap of key significant genes such as DGKA (NK and T-cell viral infection), EGR2 (T-cell viral infection and CD8 T-cell exhaustion), and the potential role of key TFs including EGR2, NFAT2 (NFATc1), and TOX2 in driving NK cell anergy." (PMID 38637625, 2024). "Although they were initially implicated in inhibition of T-cell proliferation, Egr2/3 are not generic inhibitors of T-cell proliferation but are required for clonal expansion of effector T cells in response to viral infection." (PMID 32709717, 2020). "Egr2/3 not only control inflammation but also support the homeostatic proliferation of PD-1high MP CD4 T cells and their fitness for adaptive responses to viral infection demonstrating an important function of PD-1high MP CD4 T cells in adaptive immunity." (PMID 32709717, 2020). "These functions of Egr2/3 in PD-1high MP CD4 T cells are required for the maintenance of a diverse repertoire of MP T cells, which is important for adaptive responses against viral infection." (PMID 32709717, 2020). "T cells with a single defect in either Egr2 or Egr3 did not have significant changes in expansion, proliferation, activation markers, or differentiation in response to viral infection." (PMID 28487311, 2017). "Egr2 and 3 were essential to suppress Th1 differentiation in Th2 and Th17 conditions in vitro and also to control IFN-γ–producing CD4 and CD8 T cells in response to virus infection." (PMID 28455436, 2017). "Interestingly, although Egr2/3−/− OT-II PD-1high MP cells failed to expand in response to viral infection, more of them produced IFNγ than their wild-type counterparts." (PMID 32709717, 2020). "In addition, a lack of EGR2 results in defective cloning amplification of T-cells as a response to viral infection, with overactivation and overdifferentiation." (PMID 31844579, 2019). "Furthermore, mice with a single defect in either Egr2 or Egr3 in T cells did not have impaired responses to viral infection." (PMID 28487311, 2017). "Collectively, these data indicate that the function of Egr2 and 3 in regulation of clonal expansion differs from their roles in NFAT-mediated anergy and Lag3-Treg cells, demonstrating that distinct mechanisms regulate T cells under homeostatic conditions and during viral infection." (PMID 28487311, 2017).